MYC (MYC proto-oncogene, bHLH transcription factor)
Diseases named in the same sentence as MYC in open-access papers (continued):
Sharing a sentence is not in itself a finding about the gene and the disease.
gastric tumor (27 papers, 2011 to 2026). "MYC amplification/overexpression is a recurring molecular event in gastric tumor tissues, and is often associated with an advanced tumor stage, lymph node metastasis, and low survival rates." (PMID 31645899, 2019). "In addition, MYC hypomethylation was also associated with MYC expression in gastric tumors and cell lines." (PMID 23717612, 2013). "Although we were unable to achieve statistical significance due to the low frequency of RUNX3-expressing tumors, our findings indicate a trend of inverse correlation between RUNX3 and MYC protein levels in gastric tumor." (PMID 37400551, 2023). "We compared RUNX3 and MYC protein levels in human gastric tumor tissue arrays by immunohistochemistry (IHC)." (PMID 37400551, 2023). "Some recent studies have identified typical molecular alterations, such as MYC gene (8q24) amplification, as drivers of genetic profiles characterizing advanced stages of gastric tumors, with poor prognostic features." (PMID 31645899, 2019). "When analyzed with the expression changes, the upstream regulators associated with these genes and that were predicted to be inhibited in the gastric tumors included the transcription regulators MYC and NFκB, the Pkc kinases and MAPK8 (JNK) as well as CLDN7." (PMID 31584998, 2019). "Thus, both mutations at exon 2 may affect MYC activity in gastric tumors." (PMID 23717612, 2013). "In the present study, 76.8% of gastric tumors showed MYC immunoreactivity and all tumors, intestinal and diffuse type, presented increased mRNA expression compared to their paired controls." (PMID 23717612, 2013). "In the present study, we observed three or more MYC gene copies in all gastric tumors studied, corroborating with previous studies in primary gastric tumors of individuals from our population, as well as from Eastern Asia and Europe." (PMID 23717612, 2013). "Oncogene activation, such as MYC amplification, and exposure to endogenous or therapeutic genotoxic stress further exacerbate RS in gastric tumor cells, elevating their dependency on ATR–CHK1 signaling for replication fork stabilization and cell cycle progression." (PMID 40869030, 2025). "Notably, the transcriptional features of EPO-GEMM tumors correlated with those of human gastric tumors of the respective subtypes, which was largely driven by dominant MYC, proliferation and immune-related signatures." (PMID 38177458, 2024). "MYC nuclear protein was found positive in 76.8% (96/125) of gastric tumors." (PMID 23717612, 2013). "In conclusion, our findings show that FBXW7 and MYC mRNA levels reflect the potential for aggressive biologic behavior of gastric tumors and may be used as indicators of poor prognosis in GC patients." (PMID 24053468, 2013). "Here, we observed three or more MYC gene copies in 51.5% of gastric tumors specimens." (PMID 24053468, 2013). "Three or more copies of MYC were found in 51.5% (17/33) of gastric tumor cells." (PMID 24053468, 2013). "MYC amplification was observed in 51.5% of gastric tumor samples." (PMID 24053468, 2013). "The presence of gastric tumor due to ACP03 inoculation was confirmed by MYC deregulation." (PMID 21811552, 2011). "In this study, we discovered that AFP enhances the stability of oncoproteins c-MYC and c-MET, thereby facilitating the progression of liver and gastric tumors." (PMID 39135041, 2024). "Since c-MYC protein is degraded via FBXW7-mediated ubiquitin pathway, we examined the protein expression of FBXW7 and c-MYC in gastric tumors and paired normal tissues from six patients and mouse models." (PMID 28422719, 2017). "Previously, our group demonstrated that MYC mRNA expression and copy number increases during the sequential steps of intestinal-type gastric carcinogenesis in a non-human primate model, suggesting that MYC may be involved in gastric tumor initiation and progression." (PMID 23717612, 2013).
head and neck cancer (26 papers, 2009 to 2025). A primary or metastatic malignant neoplasm affecting the head and neck. "For example, genes that play a role in the inflammatory response such as ARG1, BCL2L1 (upregulated) and MYC (downregulated) were found in blood of patients undergoing radiotherapy treatment for endometrial or head and neck cancers." (PMID 34638945, 2021). "MYC along with its co-amplified partner, CDK1 are reported to be correlated with survival and prognosis in head and neck cancers." (PMID 26808319, 2016).
clear cell renal cell carcinoma (25 papers, 2008 to 2026). "In renal clear cell carcinoma, we also detected an inverse correlation between RASSF10 and MYC expression indicating that the loss of RASSF10 is associated with MYC induction (p < 0.004)." (PMID 32047266, 2020). "Aprevious study showed that overexpression of MYC gene contributed to thecell proliferation during development of renal clear cell carcinoma." (PMID 32779435, 2020). "In addition, overexpression of HIF2α in endothelial cells results in increased MYC protein expression and HIF2α has been shown to enhance expression of MYC and promote tumor growth in renal clear cell carcinoma lines." (PMID 24236059, 2013). "Collectively, these analyses support the clinical relevance of the MYC, VM and VIM mouse models with human papillary and clear cell renal cancers." (PMID 28593993, 2017). "Our own studies highlight the role of MYC in renal tumorigenesis and demonstrate that MYC activation is sufficient to generate papillary RCC and that when combined with Vhl and Ink4a/Arf inactivation results in bona fide clear cell renal cell carcinoma." (PMID 28593993, 2017). "This may act to counter the proliferative effects of MYC, cyclin D1 and MDM2; however, and concerningly, CDKN1A is also overexpressed in clear-cell renal cell carcinoma relative to normal kidney." (PMID 24827579, 2014).
rhabdomyosarcoma (25 papers, 2006 to 2025). A rare aggressive malignant mesenchymal neoplasm arising from skeletal muscle. "Other frequently altered genes are RB1 and MYC (a well-known oncosuppressor and oncogene, respectively), NF1 (known for being often mutated in neural tumors), and PAXX (often fused with FOXO1 in alveolar rhabdomyosarcomas)." (PMID 40725011, 2025). "In rhabdomyosarcoma, MYC and YBX1 regulate each other; MYC binds to the YBX1 promoter, and YBX1 binds to MYC mRNA, forming a MYC-YBX1 circuit that maintains stem cell-like vincristine-resistant cells." (PMID 40799245, 2025). "Conversely, inactivation of ERK cascade by small molecular drugs abrogated c-MYC expression in rhabdomyosarcoma." (PMID 30001368, 2018). "As an alternate indicator of apoptosis, Western blot analyses were carried out to evaluate poly (ADP) ribose polymerase (PARP) cleavage in MYC-expressing rhabdomyosarcoma cells." (PMID 17081294, 2006). "In conclusion, molecules such as RUNX2, CBX3, and MYC interact with YBX1 to promote tumor progression in various malignant tumors, including bone cancer, pancreatic cancer, and rhabdomyosarcoma, among others." (PMID 40799245, 2025). "Other examples include rhabdomyosarcoma cells resistant to PAX3 or both PAX3 and MYOD1 KO that had an enhanced dependency on MYC compared to lineage sensitive lines." (PMID 37554444, 2023). "In rhabdomyosarcoma (RMS) cell lines, we recently demonstrated that OTX015 specifically downregulates BRD4 and MYC levels, which in turn lead to a marked downmodulation of GNL3 gene." (PMID 33806232, 2021). "Among the rhabdomyosarcomas, alterations in FGFR1, KRAS, and MYC were detected." (PMID 37726478, 2023). "Deregulated expression of oncogenes such as MYC and PAX3-FKHR often occurs in rhabdomyosarcomas." (PMID 17081294, 2006).
B-cell neoplasm (24 papers, 2012 to 2025). A group of heterogeneous lymphoid tumors generally expressing one or more B-cell antigens or representing malignant transformations of B-lymphocytes. "MYC gene alterations have been identified in B-cell neoplasms, and are usually associated with aggressive clinical behavior." (PMID 32549409, 2020). "MYC gene alterations have been identified in mature B-cell neoplasms that are usually associated with an aggressive clinical behavior." (PMID 28983465, 2017). "MYC gene alterations are common in other B-cell neoplasms and are often associated with poor outcomes." (PMID 26295308, 2016). "MYC alterations also have been identified in other mature B-cell neoplasms and are associated with aggressive clinical behavior." (PMID 26416427, 2015). "Dysregulation of phosphatidylinositol-3 kinase (PI3K) signaling is a common feature of B-cell neoplasms and contributes to MYC-driven lymphomagenesis." (PMID 33777762, 2021). "When its coding sequence is altered in B cell neoplasms, MYC is usually expressed in cells whose normal counterparts do not express it." (PMID 28375188, 2017). "In contrast, DLBCL that includes a heterogeneous group of intermediate to high-grade mature B-cell neoplasms is reported to have rearrangements of MYC in 3–16% of cases." (PMID 28983465, 2017). "MYC dysregulation also occurs in other types of B cell neoplasms, in which its expression leads to disease progression and the transformation to more aggressive forms." (PMID 28375188, 2017). "In a cohort of 156 patients with B-cell neoplasms harboring c-MYC rearrangement 33 patients (21%) carried the diagnosis of CLL." (PMID 28379189, 2017). "It has been shown that juxtaposing MYC with the immunoglobulin μ or κ enhancer in transgenic mice leads to the development of immature and mature B-cell neoplasms." (PMID 26416427, 2015). "To determine if MYC is ubiquitylated by ARF-BP1 in B cell neoplasms, we first took advantage of the P493-6 human B cell line that is derived from an EBV-immortalized B cell line and carries a conditional tetracycline-regulated MYC." (PMID 22754359, 2012). "Case 4, initially diagnosed as a mature B-cell neoplasm, was ultimately reclassified as B-ALL with MYC rearrangement and focal TdT expression." (PMID 41142614, 2025). "To examine the potential contributions of ARF-BP1 to MYC-driven B cell neoplasms, we elected to study cell lines derived from human BL and mouse DBLL from λ-MYC TG mice." (PMID 22754359, 2012). "In summary, IACS‐010759 and ascorbate synergized in vitro to kill MYC‐overexpressing mature B‐cell neoplasms, regardless of their origin and molecular subtype." (PMID 37158102, 2023).
invasive breast carcinoma (24 papers, 2012 to 2024). A carcinoma that infiltrates the breast parenchyma. "To determine if the observed alterations in BRF2 and MYC are mutually exclusive or co-occur in breast invasive carcinoma we queried the IBC data set, TCGA, Firehose Legacy in the cBioPortal." (PMID 33176745, 2020). "MAF1 amplification is frequent in invasive breast cancer and co-occurs with MYC." (PMID 37801436, 2023). "If we could combine MYC inhibitor and chemotherapy in the future, it should dramatically increase survival time of patients suffered from invasive breast cancer." (PMID 29212204, 2017). "Interestingly, an integrative genomics screen performed in 229 primary invasive breast carcinomas identified the co-amplification of MYC and the 8p11-12 cytogenetic bands, together with aberrant methylation and expression of several genes spanning the 8q12.1-q24.22 genomic region." (PMID 32907621, 2020). "In part two, we identify and validate expression and gene-related alterations of MYBL1, VCIP1, MYC and BOP1 genes in TNBC cell lines and patient samples selected from the Breast Invasive Carcinoma TCGA 2015 dataset available at cBioPortal.org." (PMID 38473786, 2024). "In this study, we demonstrate MYC and BRF2 alterations co-occur in breast invasive carcinoma, p = 0.008, as well as patients aged 46–50 with metastatic breast cancer, p = 0.053." (PMID 33176745, 2020). "In the cBioPortal Breast Invasive Carcinoma (TGCA, Firehose Legacy) data set, MYC alterations correlated with a decrease in overall survival, p = 0.0918 and co-occurring MYC and BRF2 alterations significantly decreased overall survival, p = 5.299e-3." (PMID 33176745, 2020). "c-MYC amplification, defined as a mean c-MYC copy number of 6.0 or higher, was found in 22 (7.8%) of 283 invasive breast cancer samples in the test set." (PMID 29228597, 2017). "The negative correlation between HNRNPH1 and MYC was found in multiple epithelial cancers such as breast invasive carcinoma (BRCA), COAD, lung squamous cell carcinoma, and ovarian serous cystadenocarcinoma." (PMID 37399401, 2023). "Actually, simultaneous deregulation of miR200cand miR-30c could significantly reduce the survivalrate of breast invasive carcinoma cells via up-regulationof OCT4, SOX2, c-MYC, SNAI1, ZEB1, CDH2 and down-regulation of CDH1 (P=0.02)." (PMID 31376329, 2020). "Actually, deregulation of miR‐204, miR‐200c, miR‐34a, and miR‐10b simultaneously could significantly reduce the survival rate of breast invasive carcinoma via up‐regulation of OCT4, SOX2, KLF4, c‐MYC, NOTCH1, SNAI1, ZEB1, and CDH2 and down‐regulation of CDH1." (PMID 30710426, 2019). "Notably, chr8 harbors the MYC gene, which is one of the most frequently amplified genes in human cancers, whereas chr17 contains the ERBB2 gene, which is amplified in about 20% of all invasive breast cancers." (PMID 34395272, 2021).
lymphoid neoplasm (24 papers, 2008 to 2024). A neoplasm composed of a lymphocytic cell population which is usually malignant (clonal) by molecular genetic and/or immunophenotypic analysis. "While MYC translocations are well documented in lymphoid neoplasms, the mechanisms underlying aberrant MYC activity in myeloid neoplasms have been less characterized." (PMID 37002311, 2023). "MYC gene alterations were identified initially in lymphoid neoplasms by cytogenetic and molecular genetic studies that recognized 8q24 translocations and MYC gene rearrangements, amplifications, or mutations." (PMID 26416427, 2015). "Lymphoid neoplasms with dual MYC and BCL6 rearrangements are now considered a subtype of DLBCLNOS, or HGBCL, and their gene expression profiles are highly heterogeneous and unrelated to those of DLBCL/HGB-cell lymphomas with MYC and BCL2 rearrangements." (PMID 37672206, 2024). "Lymphoid neoplasms with dual MYC and BCL6 rearrangements have been excluded from the DLBCL/HGBL-MYC/BCL2 entity and are now classified either as a subtype of DLBCL, NOS or HGBL, NOS according to their cytomorphological features." (PMID 39038016, 2024). "Activation of ERK1/2 would then lead to activation, amongst others, of MYC and hnRNPA1, two proteins previously shown to contribute to tumor formation in lymphoid neoplasms." (PMID 27303665, 2016). "All these observations suggest that MYC aberrations do also play a role in the pathogenesis of aggressive lymphoid neoplasms with terminal B-cell differentiation." (PMID 26416427, 2015). "One notable difference to cells expressing MYC alone was that the double positive CD4+CD8+ lymphoid tumor cells population was diminished among FLIPL/MYC-expressing cells in favor of the CD4+ population." (PMID 22393362, 2012). "Because MYC-IG translocations are a common feature of GC derived lymphoid tumors in humans, it is important to understand the mechanisms that lead to these translocations." (PMID 22768095, 2012). "Our results suggest that drugs blocking translation, IL-15, JAK or mTOR downstream of this cytokine might concur in the treatment of lymphoid tumors of NK cell origin depending on MYC." (PMID 37105715, 2023). "In contrast, lymphoid neoplasms with dual MYC and BCL6 rearrangements represent a more diverse spectrum with variable gene expression profiles and mutational spectra, markedly differing from DLBCL/HGBL-MYC/BCL2." (PMID 35732829, 2022). "The Eμ-MYC/BCRHEL mice provided a means to test for cooperation between signaling from the BCR and overexpression of MYC in the genesis of lymphoid tumors." (PMID 18578569, 2008). "Indeed we note high levels of MYC in the lesions, which has been shown previously to be a strong collaborating event with RUNX2 in lymphoid tumours." (PMID 24626992, 2014). "Our transcriptomic characterization supports the new, 2022 adaptation of WHO nomenclature of lymphoid tumors regarding these classes where MYC/BCL6 rearrangements are not further considered as a hit-classifier and the other two types are now defined as IRF4-R LBCL and HGBL-11q, respectively." (PMID 35884496, 2022). "Co-expression of MYC with BCL-XL or BCL-2 also influenced the tumor phenotype; Rather than a mixed phenotype of myeloid and T lymphoid tumors, development of an aggressive AML-like disease was favored." (PMID 22393362, 2012).